HIF1A (hypoxia inducible factor 1 subunit alpha)
Diseases named in the same sentence as HIF1A in open-access papers (continued):
Sharing a sentence is not in itself a finding about the gene and the disease.
endothelial dysfunction (52 papers, 2008 to 2026). In vascular diseases, endothelial dysfunction is a systemic pathological state of the endothelium (the inner lining of blood vessels) and can be broadly defined as an imbalance between vasodilating and vasoconstricting substances produced by (or acting on) the endothelium. "As serum phosphorus is a cardiovascular risk factor, these data correspond with a predisposition of Hif1α+/− mutation for endothelial dysfunction and cardiovascular disease." (PMID 28774305, 2017). "For example, in an ocular ischemia/reperfusion model in pigs where an ischemic period of 12 min was followed by 20 h of reperfusion, RGC loss, endothelial dysfunction and oxidative stress in retinal arterioles were observed together with upregulation of HIF-1α, VEGF-A, and NOX2." (PMID 38006824, 2023). "We speculate that the loss of HIF-1α from senescent endothelial cells is critical in endothelial homeostasis and thus in aging-associated diseases, such as endothelial dysfunction and vascular disease." (PMID 31089163, 2019). "Endothelial dysfunction might cause tissue hypoxia and the upregulation of HIF-1α expression." (PMID 34268320, 2021). "Collectively, the accumulated molecular effects—trophoblastic dysfunction, impaired angiogenesis, mitochondrial damage, and HIF-1α feedback—explain the clinical phenomena observed: hypoxia, chronic inflammation, and endothelial dysfunction." (PMID 41226989, 2025). "The prolonged HIF-1A expression in trophoblasts, resulted in placental disorganization, inhibition of trophoblast differentiation with endothelial dysfunction, and failed remodelling of the maternal spiral arteries." (PMID 40804807, 2025). "In in vitro model demonstrates a protective role of miR-126 in the endothelium, since its downregulation contributes to endothelial dysfunction by reducing HIF-1α (hypoxia-inducible factor 1-alpha), a factor involved in vascular repair." (PMID 41010004, 2025). "Intermittent hypoxia initiates a cascade of oxidative stress, endothelial dysfunction, and inflammation, implicating factors such as HIF-1α, VEGF, ET-1, MMPs, and neuroinflammatory cytokines." (PMID 40724899, 2025). "Elevated levels of OxLDL in the circulation and vascular wall contribute to endothelial dysfunction by downregulating eNOS expression, promoting HIF-1a accumulation, and inducing HIF-1-dependent gene activation in macrophages via the redox-mediated pathway." (PMID 41302972, 2025). "We suggest that superficial trophoblast invasion and spiral artery remodeling lead to continuous placental hypoxia which upregulates HIF-1α expression, thus leading to endothelial dysfunction and the pathogenesis of PE." (PMID 36859279, 2023). "HGG can protect against endothelial dysfunction and prevent thrombosis by regulating the expression of HIF-1α and NF-κB." (PMID 36776258, 2023). "Hypoxia inducible factors-1α (HIF1α) is known for its role in fibrosis and in endothelial dysfunction." (PMID 33969024, 2021). "HIF-1α mRNA and protein levels were examined in both early passage and senescent HUVECs to determine the mechanism of endothelial dysfunction." (PMID 31089163, 2019). "Aberrant HIF‐1α signaling contributes to endothelial dysfunction and decreased angiogenesis in PPHN." (PMID 30706701, 2019). "Aging in humans and rodent models results in a reduction in angiogenesis associated with reduced angiogenic factors such as HIF-1α and VEGF as well as endothelial dysfunction." (PMID 29447208, 2018). "Taken together, these data indicate that the IRE1α/XBP1s/HIF1α pathway activation is critical for mediating ANGII-dependent endothelial dysfunction under PM2.5 exposure." (PMID 29044123, 2017). "In summary, data in thisstudy have demonstrated that PM2.5 exposure induces endoplasmic reticulum (ER) instability, leading to the activation of IRE1α/XBP1s branch of UPR and links HIF1α transactivation to mediate ANGII-dependent endothelial dysfunction." (PMID 29044123, 2017).
endothelial dysfunction (continued). "Third, suppression of HIF-1α and hypoxia-induced vascular congestion observed in this study suggests that hydrogen may stabilize vascular function and prevent hypoxia-induced endothelial dysfunction." (PMID 41009034, 2025). "The results highlight a complex network of interrelated pathways involving HIF-1α and NF-κB activation, ROS production, antioxidant defense compromise, inflammatory cytokine release, and endothelial dysfunction, all contributing to the pathophysiological landscape of OSAS." (PMID 38672697, 2024). "Our previous investigation in porcine ischemia/reperfusion (I/R) models revealed hypoxia-associated damage, characterized by the overexpression of VEGF, iNOS, HIF-1α, and NOX2, leading to detectable high levels of O2• in retinal arterioles, ultimately causing endothelial dysfunction." (PMID 38006824, 2023). "In addition, HIF-1α induces oxidative stress and inflammatory responses to ECs, which can result in endothelial dysfunction and severe tissue damage." (PMID 34479471, 2021). "Controversially, most studies have indicated that the upregulated expression of HIF-1α was induced by tissue hypoxia due to endothelial dysfunction and deficient NO production, and the inhibition of eNOS by N-nitro-L-arginine methyl ester (L-NAME) promoted the expression of HIF-1α." (PMID 34268320, 2021). "Therefore, focusing on the HIF-1α axis and its inhibition can help design new therapies for endothelial dysfunction." (PMID 34479471, 2021). "Furthermore, in the cardiovascular system, HIF-1α stabilization via NF-κB in vascular endothelial cells promoted endothelial dysfunction in atheroprone regions." (PMID 34638942, 2021). "There have been some studies suggesting that low HIF-1α expression might be correlated with endothelial dysfunction." (PMID 34268320, 2021). "The decreased HIF1-α may mean that BH4 availability protects against endothelial dysfunction and maintains bladder blood flow by suppressing arterial wall thickening with neointimal formation in rats." (PMID 33199757, 2020). "Therefore, we conclude that PM2.5 exposure instigates endoplasmic reticulum instability, leading to the induction of IRE1α/XBP1s branch of UPR and links HIF1α transactivation to mediate ANGII-dependent endothelial dysfunction." (PMID 29044123, 2017). "Our study reveals an important molecular and cellular mechanism of hypoxia-induced endothelial dysfunction and suggests that targeting HIF1α-Arg-II-mitochondrial ROS cascade could be a promising therapeutic strategy to prevent hypoxia-induced vascular damage/dysfunction." (PMID 31474872, 2019). "Associated with the upregulation of angiogenesis‐related proteins, including VEGFR, VEGF, Erk, Nrf2, Keap1, HO‐1 and HIF‐1α, HBO treatment rescues limb ischaemia‐induced endothelial dysfunction." (PMID 39720917, 2024). "Inducing vascular endothelial cells to produce SUMO1 continuously stabilizes the HIF-1α/VEGF pathway, improves endothelial dysfunction under hypoxic conditions, and promotes angiogenesis." (PMID 34840664, 2021). "This is in line with the previous study that hypoxia induces HIF1α, arginase type II (Arg II), and ICAM-mediated signaling in ECs which ultimately leads to endothelial dysfunction." (PMID 33969024, 2021). "This decrease in miR-223 expression was regulated by increased activity of hypoxia-inducible factor 1α (HIF1α), and this in turn upregulated PARP-1 activity and contributed to endothelial dysfunction." (PMID 28660007, 2017). "Most importantly, IRE1α/XBP1s branches of UPR links hypoxia-inducible factor 1α (HIF1α) activation to mediate the local augmented RAS components and the endothelial dysfunction ensued." (PMID 29044123, 2017). "We found that SIRT6 inhibited HIF1α transcriptional activity by antagonizing p300 acetylation of H3K9 at the Ero1α promoter, thereby suppressing Ero1α expression and augmentation of ERS‐induced endothelial dysfunction." (PMID 37598403, 2023).
endothelial dysfunction (continued). "Furthermore, the result of overexpressed TLR4 and HIF‐1α was the same as vivo experiment, reversing the effect of resveratrol on inhibiting Gly‐LDL‐induced endothelial dysfunction." (PMID 34114347, 2021). "The compiled data demonstrate that, although HIF-1α promotes initial adaptive responses to hypoxia—such as angiogenesis via VEGF and anaerobic glycolysis—its prolonged or dysregulated activation exacerbates the cytokine storm, endothelial dysfunction, and viral persistence." (PMID 40362439, 2025). "According to Liu’s study, diminished HIF-1α expression during the placental ischemic process leads to excessive apoptosis, the reduced expression of VEGF and PlGF, and the overexpression of sFlt1, sEng, and TNF-α, leading to endothelial dysfunction and elevated systolic blood pressure." (PMID 41515555, 2025). "Finally, we tried to determine whether IRE1α/XBP1s/HIF1α pathway activation, which mediates augmented ACE/ANGII/AT1R axis components, also contributes to regulating ANGII-dependent endothelial dysfunction under PM2.5 exposure." (PMID 29044123, 2017). "Thus, noncanonical mechanical activation of HIF1α plays an important role in focal endothelial dysfunction and has the potential to be targeted therapeutically to enhance vascular function." (PMID 28882872, 2017).
head and neck cancer (52 papers, 2003 to 2026). A primary or metastatic malignant neoplasm affecting the head and neck. "An important finding was also the association of HIF1α with low infiltration of PCs with TILs in accordance with previous studies in breast and head–neck cancer." (PMID 37067635, 2023). "The hypoxia-induced amoeboid migration has only been described once to date and to our knowledge in a head and neck cancer model and is linked to HIF-1A." (PMID 38092743, 2023). "The highest mutation frequency of the HIF1α gene in pan-cancer was head and neck cancer, and the HIF1α methylation level in most tumors is significantly reduced." (PMID 35860430, 2022). "Hypoxia induces the stabilization of HIF‐1α, which is associated with radiotherapy resistance in head and neck carcinoma." (PMID 35415942, 2022). "This meta-analysis was implemented to evaluate the association between hypoxia-inducible factor-1α (HIF-1α) C1772T/G1790A polymorphisms and susceptibility to head and neck cancer (HNC)." (PMID 34256803, 2021). "Co-expression of HIF-1α, Snail and Twist is associated with metastasis and poor prognosis in human head and neck cancers." (PMID 31579438, 2019). "Overexpression of HIF-1α has been shown to be associated with tumor cell growth in patients with cervical, endometrial, gastric, colorectal, pancreatic, ovarian, breast, and head/neck carcinomas." (PMID 28521842, 2017). "In head and neck carcinomas, study showed that the expression of HIF-1α protein is associated with the microvessel vascular density and vascular endothelial growth factor (VEGF) expression." (PMID 25816356, 2015). "The overexpressed HIF-1α has resulted into high mortality rate in patient experiencing cancers of the breast, ovary, uterus, cervix, brain, and oropharynx, while overexpression of HIF-1α has been associated with decreased death rate with head and neck cancer patients." (PMID 31485300, 2019). "TWIST1 specifically acts as an essential downstream effector of HIF-1α in head and neck cancer, where its knockdown in HIF-1α-overexpressing cells reduces metastatic nodules in vivo." (PMID 41511366, 2026). "A crucial aspect is its ability to suppress HIF-1α activation under hypoxic conditions, suggesting its potential as an adjuvant in chemotherapy, sensitizing head and neck cancer cells to gefitinib and suppressing angiogenesis." (PMID 40507826, 2025). "The clinical outcomes of head and neck cancer patients become worse whenproducers of HIF-1α and HIF-2α elevate in their tumors." (PMID 40636217, 2025). "A link between hypoxia, EMT, and the regulation of MT4-MMP expression has been evidenced in head and neck cancer where SLUG contributes to HIF-1α dependent MT4-MMP." (PMID 37373092, 2023). "In fact, invadopodia formation and amoeboid movements, which are both crucial mechanisms to promote metastatic dissemination, are mediated by HIF1-α-induced MT4-MMP expression in head and neck cancer tumor cells." (PMID 37373092, 2023). "As tumor hypoxia is the largest determinant in treatment-efficacy variability in survival in head and neck cancers many endogenous markers such as HIF1A/HIF1α, CA9/CAIX, SLC2A1/GLUT1, have been investigated." (PMID 34904929, 2022). "As tumor hypoxia is the largest determinant in treatment-efficacy variability in survival in head and neck cancers many endogenous markers such as HIF1A, CA9, SLC2A1 and others, have been investigated." (PMID 34904929, 2022). "For example, lncRNA MIR31HG regulated cell cycle progression via HIF1A and p21 and facilitated head and neck cancer cell proliferation and tumorigenesis." (PMID 33391449, 2021). "HIF1A functioned in the proliferation of head and neck cancer cells by regulating the cell cycle progression." (PMID 33663502, 2021). "To determine the functionality of HIF-1α in head and neck cancer cells, we investigated its cellular localization." (PMID 29163780, 2017).
head and neck cancer (continued). "Data showed that HIF-1α overexpression is correlated with poorer survival in oligodendroglioma, endometrial, uterine cervical, ovarian, esophageal, lung, head and neck cancer." (PMID 27780920, 2016). "Hypoxia of head and neck cancer most likely occurs if the transfection of the hypoxic gene HIF-1α also results in the transfer of Twist and Snail genes, resulting in the worst prognosis in patients." (PMID 27391337, 2016). "A few studies concerning HIF-1α expression in relation to tumor behavior and prognosis in head and neck carcinomas also confirm our findings." (PMID 25412955, 2015). "Stratified analysis of pooled hazard ratios for head and neck cancer with overexpressed Hif-1α and Hif-2α." (PMID 24058651, 2013). "The relationship between HIF1α expression, tumor progression and treatment response in head and neck cancer is still poorly understood." (PMID 23028863, 2012). "Furthermore, hypoxia‐induced HIF1α activation promotes calpain 2, leading to the enzymatic cleavage of talin‐1 and β1 integrin, which facilitates amoeboid migration of breast and head and neck cancer cells." (PMID 40151834, 2025). "In addition, MIR31HG targeted HIF1A and P21 to facilitate head and neck cancer cell proliferation and tumorigenesis by promoting cell cycle progression." (PMID 37029420, 2023). "The strongest effect of ascorbate dependent downregulation of HIF-1α target genes expression was also observed for CA9 in head and neck carcinoma cell line 22B (more than 75-fold decrease in CA9 compared to a 25-fold decrease for GLUT3 and a 50-fold decrease for MMP-2)." (PMID 29100428, 2017). "Moreover, several studies have reported on HIF-1α overexpression-related radioresistance in head and neck cancers." (PMID 27285985, 2016). "The contribution of glucose transporter (GLUT) and hypoxia-inducible factor-1α (HIF-1α) activity to tumor behavior and their prognostic value in head and neck cancers remains unclear." (PMID 25412955, 2015). "Among them, 6 genes were highly expressed in head and neck cancers, namely SLC1A5, ETS1, NDRG1, RHEB, HIF1A and CDH2." (PMID 41317550, 2025). "CONCLUSIONS: We conclude that HIF1A-induced nuclear UCA1 stimulated cell migration and invasion via interacting with PTBP3, increasing lymph node metastasis in head and neck cancer." (PMID 41068676, 2025). "Furthermore, the miRNAs did not affect HIF-1α expression, which is consistent with the well-known role of hypoxia in stem cell maintenance and the association between tumor hypoxia and CSCs, as observed in breast and head and neck cancers." (PMID 36982993, 2023). "This laboratory is the first to show that therapeutic dose of selenium as highly effective inhibitor of both constitutively expressed HIF-1α, HIF-2α in ccRCC and hypoxia induced HIF-1α in head & neck cancer." (PMID 22804960, 2012). "Besides, over-expression of hypoxia-induced factor-1 α (HIF-1α) induces EMT and metastasis in cancers such as head and neck cancer." (PMID 31579438, 2019). "However, it has been reported that HIF-1α overexpression was not significantly correlated with pathological parameter in other cancers, including head and neck cancer, and oropharyngeal cancer." (PMID 12966423, 2003).